GK3 (glycerol kinase 3)
Description:
May be involved in the regulation of glycerol uptake and metabolism.
Synonyms: GK3P; GKP3; GKTB
Tractability: Antibody: UniProt places it where antibodies can reach, with medium confidence. PROTAC: ubiquitination databases record sites on it.
Gene: Protein-coding gene on chromosome 4 (165,277,807 to 165,279,704, reverse strand). Ensembl gene ENSG00000229894.
Subcellular location: Mitochondrion outer membrane; Cytoplasm
Pathways (Reactome):
Metabolism: Triglyceride biosynthesis
Gene Ontology:
Molecular function: glycerol kinase activity; kinase activity; phosphotransferase activity, alcohol group as acceptor
Biological process: glycerol-3-phosphate biosynthetic process; triglyceride metabolic process; carbohydrate metabolic process; glycerol catabolic process; glycerol-3-phosphate metabolic process
Cellular component: mitochondrion; cytoplasm; mitochondrial outer membrane
Genetic constraint (gnomAD): Loss-of-function variants: 2 observed, 4.94 expected, observed/expected ratio (o/e) 0.4, 90% interval 0.16 to 1.26. That is too few expected variants to judge how well the gene tolerates losing a copy. Missense variants: 118 observed, 139.67 expected, observed/expected ratio (o/e) 0.84, 90% interval 0.73 to 0.98. Synonymous variants: 45 observed, 53.46 expected, observed/expected ratio (o/e) 0.84, 90% interval 0.66 to 1.08.
Homologues: Orthologues: chimpanzee GK3 (99% identical), guinea pig Gk (97% identical), mouse Gk (96% identical), rat Gk (96% identical), macaque GK3 (92% identical), tropical clawed frog gk (84% identical), zebrafish GK2 (75% identical), Drosophila melanogaster Gk2 (48% identical), Caenorhabditis elegans R11F4.1 (46% identical), Drosophila melanogaster CG8298 (41% identical). Paralogues in human: GK (99% identical), GK2 (88% identical), GK5 (31% identical), FGGY (20% identical), SHPK (15% identical), XYLB (14% identical).